FAM171A2 (family with sequence similarity 171 member A2)
Synonyms: MGC34829
Tractability: Antibody: UniProt predicts a signal peptide or a membrane-spanning region. PROTAC: ubiquitination databases record sites on it; its protein half-life has been measured.
Gene: Protein-coding gene on chromosome 17 (44,353,215 to 44,363,868, reverse strand). Ensembl gene ENSG00000161682.
Subcellular location: Membrane
Gene Ontology:
Cellular component: membrane
Genetic constraint (gnomAD): Loss-of-function variants: 12 observed, 32.47 expected, observed/expected ratio (o/e) 0.37, 90% interval 0.24 to 0.6. The upper end of that interval is the gene's LOEUF score, 0.6, which puts it in group 2 of 6, group 1 being the genes least tolerant of losing a copy. Missense variants: 938 observed, 860.65 expected, observed/expected ratio (o/e) 1.09, 90% interval 1.03 to 1.15. Synonymous variants: 467 observed, 398 expected, observed/expected ratio (o/e) 1.17, 90% interval 1.09 to 1.27.
Homologues: Orthologues: chimpanzee FAM171A2 (99% identical), macaque FAM171A2 (99% identical), pig FAM171A2 (95% identical), dog FAM171A2 (94% identical), rat Fam171a2 (94% identical), mouse Fam171a2 (94% identical), guinea pig FAM171A2 (69% identical), tropical clawed frog fam171a2 (58% identical), zebrafish fam171a2a (48% identical), zebrafish fam171a2b (43% identical). Paralogues in human: FAM171A1 (40% identical), FAM171B (27% identical).
Diseases named in the same sentence as FAM171A2 in open-access papers:
FAM171A2 is named in the same sentence as 10 diseases in open-access papers, as found by Europe PMC text mining. Sharing a sentence is not in itself a finding about the gene and the disease. The quoted sentences say what the papers report.
breast carcinoma (1 paper, 2019). "Additionally, we found genes highly expressed in breast cancer stroma in the Human Protein Atlas (EGR1, OSBPL8, FAM171A2, FGD6, and CEP131), or likely expressed in fibroblasts (MMP13), that are reported to play a role in breast cancer progression among the most important ones." (PMID 31505876, 2019).
endometrial carcinoma (1 paper, 2025). A malignant tumor arising from the epithelium that lines the cavity of the uterine body. "While FAM171A2 mRNA levels are elevated in ovarian carcinoma and modestly altered in endometrial carcinoma, protein expression remains low, indicating a discrepancy between transcription and translation." (PMID 41303609, 2025). "Importantly, this study provides the first integrated, multi-dataset analysis of FAM171A2 in ovarian and endometrial cancer, establishing a foundation for future mechanistic and translational investigations." (PMID 41303609, 2025).
gynecological cancers (1 paper, 2025). "FAM171A2 demonstrates context-dependent expressions that are modulated post-transcriptionally in gynecologic cancers." (PMID 41303609, 2025). "The limited upregulation of FAM171A2 in gynecological cancers, particularly OV, as compared to other tumor types, underscores its potential as a tissue-specific biomarker." (PMID 41303609, 2025). "Further functional validation through cell-based and animal models will be critical to elucidate its mechanistic role and assess whether FAM171A2 or its regulatory RNA network can serve as a novel biomarker or therapeutic target in gynecologic cancers." (PMID 41303609, 2025). "Collectively, these findings propose that FAM171A2 may act as a convergence point for neuronal and immune signaling in gynecological cancers, a novel concept warranting further experimental validation." (PMID 41303609, 2025). "In support of this, our TargetScan analysis identified >200 miRNAs potentially regulating FAM171A2, including the miR-15/16/195/497 family, well-known regulators of apoptosis, proliferation, and EMT in gynecological cancers." (PMID 41303609, 2025). "Together with proteomic evidence showing that both proteins localize to membrane-associated structures involved in motility and structural remodeling, these findings provide biological plausibility for our hypothesis that FAM171A2 and NPTX1 may converge on similar pathways in gynecologic cancers." (PMID 41303609, 2025). "Thus, post-transcriptional dysregulation of FAM171A2 could represent a non-canonical but biologically relevant mechanism contributing to gynecologic cancer progression." (PMID 41303609, 2025).
melanoma (1 paper, 2020). A malignant, usually aggressive tumor composed of atypical, neoplastic melanocytes. "The transmembrane protein FAM171A2 induces membrane protrusions in cultured cells upon overexpression and is required for invasive growth of melanoma cells." (PMID 33057002, 2020).
ovarian carcinoma (1 paper, 2025). A malignant neoplasm originating from the surface ovarian epithelium. "In ovarian cancer (OV), where late-stage diagnosis and chemoresistance present significant challenges, FAM171A2 has been identified as a potential molecule associated with the extracellular matrix (ECM)." (PMID 41303609, 2025). "Our analysis reveals an inverse correlation between UCA1 and FAM171A2 expression, suggesting that UCA1-mediated oncogenic signaling may suppress FAM171A2-associated regulatory pathways, thereby enhancing drug resistance mechanisms in ovarian cancer cells." (PMID 41303609, 2025). "Notably, PVT1 has been implicated in ovarian cancer tumorigenesis and proposed as a promising diagnostic and therapeutic target, The negative correlation with FAM171A2 may indicate a compensatory or antagonistic function within tumor progression pathways." (PMID 41303609, 2025).
ovarian serous cystadenocarcinoma (1 paper, 2025). A malignant serous cystic epithelial neoplasm arising from the ovary. "Scatter plots show the correlations between FAM171A2 mRNA expression and six lncRNAs (BACE1-AS, GAS5, HOTAIR, HOXA10-AS, PVT1, and UCA1) in ovarian serous cystadenocarcinoma samples (n = 379) from the ENCORI database." (PMID 41303609, 2025).
tumor (2 papers, 2019 to 2025). "Given the context of gynecological malignancies, these associations may indicate unexplored functions of FAM171A2 in tumor microenvironment regulation, immune crosstalk, and possibly neuro-immune signaling within cancer biology." (PMID 41303609, 2025). "Collectively, these findings indicate the presence of tumor-type-specific ceRNA networks, wherein distinct sets of miRNAs and lncRNAs modulate FAM171A2 expression." (PMID 41303609, 2025). "In summary, this study presents the inaugural integrative characterization of FAM171A2 across gynecologic malignancies, revealing tumor-type-specific expression patterns and distinct post-transcriptional regulatory signatures." (PMID 41303609, 2025). "Our comprehensive multi-platform analysis identified tumor-type–specific expression variations, a notable discrepancy between transcriptomic and proteomic levels, and novel interaction networks connecting FAM171A2 to neuronal and immune pathways." (PMID 41303609, 2025). "Overall, tumor tissues showed higher FAM171A2 expression than normal endometrium across strata." (PMID 41303609, 2025). "Although direct experimental evidence for FAM171A2 is currently limited, transcriptomic profiling from large-scale cancer datasets (e.g., TCGA) indicates differential expression patterns across multiple tumor types, further supporting its potential role in cancer pathogenesis." (PMID 41303609, 2025). "Moreover, integration with single-cell and spatial transcriptomics may help resolve FAM171A2-mediated communication within tumor, immune, and stromal compartments." (PMID 41303609, 2025). "Thus, elevated FAM171A2 transcripts may serve as a molecular indicator of aggressive tumor behavior or altered EV communication." (PMID 41303609, 2025). "Furthermore, given its predicted involvement in vesicle trafficking and RNA-based regulatory interactions, FAM171A2 may contribute to EV-mediated communication, which plays a critical role in tumor invasion, immune crosstalk, and chemoresistance." (PMID 41303609, 2025). "EGR1, OSBPL8 (encoded by the gene KIAA1451), FAM171A2, FGD6, and CEP131 showed particularly high or largely exclusive staining in stromal cells, supporting the notion that indeed the expression profile of CAFs drives tumor classification in our random forest model." (PMID 31505876, 2019). "Our findings indicate that FAM171A2 is more intricately involved in the EMT-driven biological processes of OV than in the canonical oncogenic pathways of UCEC, aligning with the tumor-type–specific oncogenic dependencies." (PMID 41303609, 2025). "Although FAM171A2 was not independently prognostic for overall survival, its association with neuronal and immune-related gene modules suggests potential involvement in cell–cell communication, extracellular vesicle biology, and tumor microenvironmental remodeling." (PMID 41303609, 2025). "In light of the absence of previous research on FAM171A2 within oncological frameworks, investigating its transcriptional and post-transcriptional regulation could yield novel insights into tumor biology." (PMID 41303609, 2025).
cancer (1 paper, 2025). A tumor composed of atypical neoplastic, often pleomorphic cells that invade other tissues. "Pan-cancer analysis using the TNMplot platform revealed variable expression patterns of FAM171A2 across malignancies." (PMID 41303609, 2025). "TIMER2 analysis revealed that FAM171A2 expression was significantly upregulated in several cancer types." (PMID 41303609, 2025). "FAM171A2’s neuronal functions may have biologically relevant parallels in cancer." (PMID 41303609, 2025). "Although FAM171A2 protein levels are low, the post-transcriptional regulation observed in our analysis suggests that FAM171A2 may participate in cancer progression through RNA-based mechanisms rather than through protein abundance alone." (PMID 41303609, 2025). "Therefore, although FAM171A2 has not been previously characterized in the context of cancer, its structural attributes and functional similarities to signaling and adhesion molecules offer a biologically plausible rationale for its investigation in gynecologic malignancies." (PMID 41303609, 2025).
gynecologic tumor (1 paper, 2025). "Thus, the neuronal characteristics of FAM171A2 may endow gynecologic tumor cells with enhanced adaptability within neural and immune niches, providing a biologically plausible basis for its dual functional signature." (PMID 41303609, 2025). "Thus, FAM171A2 may act as a transcript-level regulatory node, influencing gynecologic tumor behavior without requiring high protein expression." (PMID 41303609, 2025).
FAM171A2 also shares sentences with these, for which no sentence is quoted: uterine corpus endometrial carcinoma (1 paper).